CLDN11 (claudin 11)
Diseases named in the same sentence as CLDN11 in open-access papers (continued):
Sharing a sentence is not in itself a finding about the gene and the disease.
osteosarcoma (2 papers, 2023 to 2025). A usually aggressive malignant bone-forming mesenchymal neoplasm, predominantly affecting adolescents and young adults. "This study identifies EPYC, CLDN11, and STOM for the first time as biomarkers associated with the prognosis of osteosarcoma." (PMID 40075313, 2025). "The five biomarkers (CD36, CLDN11, EPYC, PANX3, and STOM) were screened to construct an AAMRGs risk model with prognostic value, providing a new reference for the prognosis and treatment of osteosarcoma." (PMID 40075313, 2025). "The differential analysis showed that in the osteosarcoma group, the expression of EPYC and PANX3 was obviously elevated, whereas the expression of CD36, CLDN11 and STOM was markedly decreased." (PMID 40075313, 2025). "Validation of gene expression through public databases and RT-qPCR results showed significant upregulation of EPYC and PANX3 in osteosarcoma samples, while CD36, CLDN11, and STOM were significantly downregulated." (PMID 40075313, 2025). "In addition, CD36, CLDN11 and STOM were found to have lower expression between osteosarcoma tissue samples compared to para-carcinoma tissue." (PMID 40075313, 2025). "The roles of PANX3 and CD36 are well established; however, the specific functions of EPYC, CLDN11, and STOM in osteosarcoma remain unclear." (PMID 40075313, 2025). "In order to develop a risk model with the optimal prognostic predictive capacity of these DE-AAMRGs in osteosarcoma patients, we performed univariate Cox analysis and utilized the LASSO method to select a panel of five biomarkers (CD36, CLDN11, EPYC, PANX3, and STOM)." (PMID 40075313, 2025).
ovarian carcinoma (2 papers, 2021 to 2024). A malignant neoplasm originating from the surface ovarian epithelium. "In line with the sequencing data, our investigation discovered that ginger inhibited the expression of CLDN7, CLDN11, and CD274 in ovarian cancer cells SKOV3." (PMID 38575994, 2024). "Ginger inhibits ovarian cancer cells’ SKOV3 invasion by regulating m6A methylation through CLDN7, CLDN11, and CD274." (PMID 38575994, 2024). "Furthermore, three genes showed low expression in the ovarian cancer samples compared with normal tissue samples and included CLDN5, CLDN11, and CLDN15." (PMID 34249076, 2021). "Therefore, altering the m6A methylation levels of CLDN7, CLDN11, and CD274, which in turn affects the growth of SKOV3 in ovarian cancer cells may be one of the mechanisms by which ginger resists ovarian cancer cells SKOV3." (PMID 38575994, 2024). "Therefore, by altering the m6A methylation levels of CLDN7, CLDN11, and CD274, which in turn affects the multiplication of ovarian cancer cells SKOV3 may be one of the mechanisms by which ginger is anti-SKOV3." (PMID 38575994, 2024).
Ataxia (1 paper, 2012). Ataxia refers to impaired coordination of voluntary muscle movement. "Interestingly, it has been shown that the mice deficient for claudin-11 or caspr present myelin and TJ disorganization, alterations in locomotion coordination and/or severe ataxia." (PMID 22363515, 2012).
atrophic gastritis (1 paper, 2017). "The result showed that the expression of claudin-11, -23 in atrophic gastritis was significantly lower than that in paracancerous atrophic gastritis (P = 0.005, P = 1.21*10−5 respectively)." (PMID 28350854, 2017). "Moreover, we found an interesting phenomenon that the expression of claudin-11, -23 in atrophic gastritis was significantly lower than that in paracancerous atrophic gastritis." (PMID 28350854, 2017). "In addition, we compared the expression of claudin-11, -23 between atrophic gastritis and paracancerous atrophic gastritis." (PMID 28350854, 2017). "In addition, as an important precancerous disease, we found that the expression of claudin-11, -23 was also significantly lower in atrophic gastritis than superficial gastritis." (PMID 28350854, 2017).
Azoospermia (1 paper, 2022). Absence of any measurable level of sperm,whereby spermatozoa cannot be observed even after centrifugation of the semen pellet. "In nonobstructive azoospermia patients, claudin-11, occludin, and ZO-1 are associated with increased apoptosis and unstained/irregular TJ development." (PMID 36071829, 2022). "The proportion of men with nonobstructive azoospermia with an aberrant claudin-11 expression pattern, particularly those with Sertoli cell-only syndrome, is substantially higher than that of men with obstructive azoospermia." (PMID 36071829, 2022).
Cerebral ischemia (1 paper, 2023). Restriction of arterial blood supply to the brain associated with insufficient oxygenation to support the metabolic requirements of the tissue. "Compared to WT mice, Lrg1−/− mice exhibited increased protein levels of cell adhesion-related molecules, including Cldn11, Anxa2, Pcdh9, and Itgb5, in endothelial cells after cerebral ischemia‒reperfusion injury." (PMID 38037097, 2023). "Single-cell RNA sequencing analysis of WT and Lrg1−/− mouse brain tissues after cerebral ischemia‒reperfusion injury revealed that Lrg1 knockout enhances blood‒brain barrier (BBB) by upregulating claudin 11, integrin β5, protocadherin 9, and annexin A2." (PMID 38037097, 2023). "We believe that Lrg1 knockout may regulate the expression of critical junction molecules, such as Cldn11 and Anxa2, affecting their protein expression and ultimately preserving BBB stability after cerebral ischemia‒reperfusion injury and reducing brain edema." (PMID 38037097, 2023).
colonic carcinoma (1 paper, 2017). "For instance, claudin-11 expression was higher in normal cholecyst tissues than that in cholecyst carcinoma tissues, whereas claudin-23 expression was downregulated in colonic carcinoma." (PMID 28350854, 2017).
craniosynostosis (1 paper, 2023). Craniosynostosis is defined as the premature fusion of one or more cranial sutures leading to secondary distortion of skull shape resulting in skull deformities with a variable presentation. "CLDN11 was significantly increased, compared to controls, in coronal craniosynostosis in males, and was one of the top three increased genes in our male-stratified coronal craniosynostosis model." (PMID 36982425, 2023). "Although this gene has not previously been associated with craniosynostosis, CLDN11 is robustly expressed during osteoblast differentiation." (PMID 36982425, 2023).
dermatitis (1 paper, 2009). An inflammatory process affecting the skin. "While the distribution of Cldn6, Cldn11, Cldn12 and Cldn18 corresponded to the expanded suprabasal compartment of the dermatitis-affected Inv-Cldn6-CΔ196 epidermis, immunostaining was less intense and membranous localization less evident in lower suprabasal layers." (PMID 19915705, 2009).
diabetes (1 paper, 2018). "To assess the influence of diabetes and hypothyroidism on the maintenance of this junction, we detected the localization of Claudin-11 in the testes through immunohistochemistry (IHC)." (PMID 29940839, 2018). "To further evaluate the effect of hypothyroidism and diabetes on the tight junction of BTB, we performed a quantitative analysis of the Claudin-11 protein in the IHC sections." (PMID 29940839, 2018). "Although many researchers has examined the testicular cell development and sperm production of male animals under diverse disease conditions, however, the data are found lacking for the expression and immunolocalization of Claudin-11 in the testis of diabetes and hypothyroid mice." (PMID 29940839, 2018).
hearing loss (1 paper, 2024). "Among the 163 upregulated genes, we did not observe a clear enrichment of Gene Ontology processes but did obtain significant enrichment of genes associated with hearing loss, including the upregulation of Otof, Tectb, Cldn11, Sall1, Cldn14, Chrna10, Esprn, and Fgfr3." (PMID 38564333, 2024).
hepatocellular carcinoma (1 paper, 2021). A malignant tumor that arises from hepatocytes. "Moreover, miR-99b-induced downregulation of CLDN11 promoted metastasis of hepatocellular carcinoma." (PMID 33714203, 2021).
inner ear disease (1 paper, 2017). "The intrastrial space is separated by an unbroken fortification of TJ protein, and its lack of redundancy may suggest that cochlear function rely on Claudin-11, thereby playing an important role in human inner ear disease." (PMID 28848383, 2017).
liver fibrosis (1 paper, 2025). "SPP1, GNMT, CLDN11, and THBS2 were determined in the transformation process of MASH to liver fibrosis." (PMID 38726780, 2025). "Four genes (SPP1, GNMT, CLDN11, and THBS2) were the intersection genes with the potential to affect the transformation process of MASH to liver fibrosis." (PMID 38726780, 2025). "In this study, we utilized four public GEO datasets to obtain four genes (SPP1, GNMT, CLDN11, and THBS2) affecting the transformation of MASH to hepatic fibrosis." (PMID 38726780, 2025).
lymph node metastasis (1 paper, 2021). "Our findings implied that lymph node metastasis-prone subclones are more likely to share CLDN11, which is a member of the tight junction protein family that functions as a component of cell adhesion." (PMID 33441952, 2021).
Obesity (1 paper, 2025). Accumulation of substantial excess body fat. "A recombinant adeno-associated virus carrying CLDN11 was used to treat experimental obesity-related SAP." (PMID 39856555, 2025). "Mechanistically, an increase in TNF-α impaired the stability of IGF2BP3-dependent CLDN11 mRNA in obesity-related SAP." (PMID 39856555, 2025). "Both IGF2BP3 and CLDN11 were downregulated in the intestinal epithelium of patients with obesity-related SAP." (PMID 39856555, 2025). "We evaluated intestinal permeability and the expression of CLDN11 in experimental obesity-related SAP." (PMID 39856555, 2025). "Anti-TNFα therapy reduced intestinal permeability, alleviated pancreatitis, and improved the expression of IGF2BP3 and CLDN11 in intestinal epithelial cells in experimental obesity-related SAP." (PMID 39856555, 2025). "Downregulation of CLDN11 was observed in the intestinal epithelial cells of experimental obesity-related SAP." (PMID 39856555, 2025). "When the expression of CLDN11 in intestinal epithelial cells of experimental obesity-related SAP was increased exogenously, intestinal epithelial permeability and pancreatic inflammation were relieved." (PMID 39856555, 2025). "Overall, an increase in TNF-α impaired the stability of IGF2BP3-dependent CLDN11 mRNA in obesity-related SAP, aggravating intestinal permeability and pancreatic inflammation." (PMID 39856555, 2025). "Overall, the TNF-α/IGF2BP3/CLDN11 axis was involved in the mechanism of obesity-mediated SAP exacerbation and suggests potential therapeutic targets." (PMID 39856555, 2025). "However, research on the specific roles and regulatory mechanisms of CLDN11 in obesity-related SAP remains limited." (PMID 39856555, 2025). "CLDN11 regulates intestinal permeability in obesity-related SAP." (PMID 39856555, 2025). "Therefore, we investigated the role and mechanism of CLDN11 in the intestinal epithelial cells of obesity-related SAP." (PMID 39856555, 2025). "However, the role and mechanism of CLDN11 in the intestinal permeability of obesity-related SAP remain unclear." (PMID 39856555, 2025). "In our study, obesity exacerbated SAP by increasing intestinal permeability and bacterial translocation, with CLDN11 as a key molecule in increasing intestinal permeability." (PMID 39856555, 2025). "To explore the mechanism of CLDN11 mRNA in obesity-related SAP, we utilized an online software tool, catRAPID, to predict protein-CLDN11 mRNA pairs." (PMID 39856555, 2025). "Under the effect of TNF-α in obesity-related SAP, the transcription and translation of IGF2BP3 in intestinal epithelial cells were inhibited, thereby affecting the expression of CLDN11." (PMID 39856555, 2025). "To understand the role of CLDN11 in the intestinal permeability of obesity-related SAP, we induced AAV-mediated overexpression of CLDN11." (PMID 39856555, 2025). "In this study, we aimed to clarify the role of CLDN11 in the intestinal epithelial cells of obesity-related SAP and investigate the regulatory mechanism of IGF2BP3 on CLDN11 under inflammatory conditions." (PMID 39856555, 2025).
oral cancers (1 paper, 2023). "In oral cancers, snail-induced claudin-11 promotes collective migration, thereby promoting cancer invasion and tumor cluster circulation." (PMID 36737832, 2023).
ovarian serous adenocarcinoma (1 paper, 2009). An adenocarcinoma that arises from the ovary and is characterized by the presence of malignant epithelial cells that, in well differentiated tumors, resemble the epithelium of the fallopian tube or, in poorly differentiated tumors, show anaplastic features and marked nuclear atypia. "The LCM data set shows over-expression of CLDN11, MYNN, PRKCI, and SKIL in ovarian serous adenocarcinoma." (PMID 19419571, 2009).
pancreatitis (1 paper, 2025). Inflammation of the pancreas. "Administration of antiTNFα therapy significantly improved intestinal permeability and pancreatitis and upregulated the IGF2BP3 and CLDN11 expression." (PMID 39856555, 2025).
Sertoli Cell-Only Syndrome (1 paper, 2022). A type of male infertility in which no germ cells are visible in any of the biopsied SEMINIFEROUS TUBULES (type I) or in which germ cells are present in a minority of tubules (type II). "In men with defective spermatogenesis, the claudin-11 pattern is strong, but the fraction of localization is changed in Sertoli cell-only syndrome and primary spermatocyte maturation arrest." (PMID 36071829, 2022).
skin tumors (1 paper, 2020). "However, a study using human cell lineage, obtained from cSCC, claudin-11 was overexpressed in keratinized areas of well and moderately differentiated skin tumors, evolving with loss of its expression in undifferentiated cSCC44." (PMID 32518268, 2020).
Stroke (1 paper, 2021). Sudden impairment of blood flow to a part of the brain due to occlusion or rupture of an artery to the brain. "Claudin-11 in the CC: A significant increase was observed after stroke and this effect was diminished by CORT administration (stroke FC = 3.078 vs. stroke + CORT FC = 0.6784, p < 0.001)." (PMID 34206635, 2021). "However, both CORT groups (sham + CORT and stroke + CORT) displayed significantly reduced levels of Claudin-11 (sham FC = 1 vs. sham + CORT FC = 0.2947, p < 0.05 and stroke FC = 0.8917 vs. stroke + CORT FC = 0.2596, p < 0.05)." (PMID 34206635, 2021). "Claudin-11 in the CST: Stroke did not affect the expression of Claudin-11 in the CST." (PMID 34206635, 2021).
X-linked intellectual disability (1 paper, 2022). An X-linked intellectual deficiency in which not enough information is known, reported or published to indicate whether a gene causes non-syndromic or syndromic presentations. "It is reported that AMMECR1 is associated with growth, bone, and heart alterations; CLDN11 is an epigenetic biomarker for malignancy, and THOC2 mutations are related to X-linked intellectual disability." (PMID 35879975, 2022).
tumor (32 papers, 2013 to 2025). "The regulatory axis Snail-claudin-11 influences the formation of circulating tumor cell clusters, which are associated with tumor progression." (PMID 37799140, 2023). "The function of claudin-11 in cancer cells has been mostly associated with its tumor suppressor function." (PMID 24009024, 2013). "The expression of CLDN11 is may be higher in the tumor microenvironment which ultimately associated with immunosuppression and poor prognosis in the COAD." (PMID 37799140, 2023). "The reduction in CLDN11 expression is associated with increase in invasiveness in multiple cancer types; the reintroduction of this gene reverses the cancerous phenotype, suggesting that CLDN11 has a tumor suppressive role." (PMID 29747653, 2018). "In TNBC, miR205-5p functions as a tumor suppressor and predominantly targets oncogenic genes, including CLDN11, HOXD9, and HMBG." (PMID 35804829, 2022). "The function of claudin-11 and E-Cadherin in the collective migration for tumour progression has been reported." (PMID 36291586, 2022). "While CLDN11 is perhaps the best-studied claudin in oncogenic contexts to date, it has yet to be identified as either a promoter or repressor of tumor growth." (PMID 35281827, 2022). "The authors proposed the novel idea that claudin-11 contributes to the maintenance of cell–cell contacts during tumour metastasis to enhance metastatic efficiency." (PMID 36291586, 2022). "Recently, a study of 10 human SCC cell lines showed that Snail-induced claudin-11 prompts collective migration for tumour progression." (PMID 36291586, 2022). "We suggest that CLDN1 or CLDN11 overexpression impaired tumor sensitivity to anticancer drugs mediated by interference with penetration of the drugs into inner areas of the spheroid." (PMID 31551535, 2019). "Of the proteins validated orthogonally by fmIHC, in situ analysis suggested that Arhgap33 and Claudin-11 were probably less abundant in TAB due to displacement of neural tissue by the expanding tumour." (PMID 31121957, 2019). "A paired normal tissue (#7 N) already demonstrated hyperplasia condition (presence of ≥4 cell layers above the basement membrane); nevertheless, CLDN11 expression remained relatively higher compared with its tumor tissue." (PMID 29747653, 2018). "Methyl binding domain (MBD)-ChIP sequencing of NPC cells, microarray data of NPC biopsies and gene ontology analysis were conducted to identify a potential tumor suppressor gene CLDN11 that was both hypermethylated and downregulated in NPC." (PMID 29747653, 2018). "The results showed that CLDN11 promoter was hypermethylated in seven NPC tumor tissues (34.62%–85.34%, average 62.64%) compared with that of the paired adjacent normal tissues (1.20%–42.07%, average 10%)." (PMID 29747653, 2018). "It indicated that CLDN11 was unfavorable for the anti-tumor immune process." (PMID 37799140, 2023). "Several studies have shown that CLDN11 is related to tumour migration and metastasis." (PMID 33441952, 2021). "Also claudin-11 was described to be characteristic for mesodermal cells during embryo development and tumor cell migration." (PMID 33195222, 2020). "In this study, elevated promoter methylation of claudin-11 in tumor tissues was observed." (PMID 31861759, 2019). "Also, the expression of claudin-11 has been suggested as a biomarker for advanced-stage cutaneous squamous carcinoma, and reflects the distinct stages of tumor development and differentiation." (PMID 31861759, 2019). "Thus, CLDN11 functions as a potential tumor suppressor gene and silencing of CLDN11 by DNA hypermethylation promotes NPC progression." (PMID 29747653, 2018). "However, other TJ proteins such as occludin and claudin-11 have been detected in CAFs of other tumor types." (PMID 29134439, 2018). "Anti-tumor activity of the CLDN11 was elucidated by in vitro functional assay." (PMID 29747653, 2018). "Further studies are necessary to elaborate the exact tumor suppressor function of CLDN11." (PMID 26198249, 2015).